ABCG5 (ATP binding cassette subfamily G member 5)
Diseases named in the same sentence as ABCG5 in open-access papers (continued):
Sharing a sentence is not in itself a finding about the gene and the disease.
atherosclerosis (24 papers, 2009 to 2025). A disease characterized by the build-up of fatty material and calcium deposition in the arterial wall resulting in partial or complete occlusion of the arterial lumen. "Patients on long-term treatment with phytosterols must be checked for their genetic polymorphisms in NPC1L1 and ABCG5/G8 transport proteins in order to avoid phytosterol aggregation and induction of atherosclerosis." (PMID 40004982, 2025). "Although plant sterols, once absorbed, can promote atherosclerosis, their intake is believed to be safe because of poor absorption, except in rare hyperabsorbers with homozygous ABCG5/8 mutations." (PMID 35730985, 2022). "The main difference in frequency was observed for ABCG8 rs4299376, which is consistent with previous findings indicating that a common single polymorphism in ABCG5/8 modulates plasma lipid concentrations in FH patients and influences atherosclerosis risk." (PMID 32942679, 2020). "In the atherosclerosis-susceptible strain, ABCG5 expression regressed significantly and positively on plasma LDL level, whereas DHCR7 and SQLE expression regressed significantly and negatively on plasma triglyceride level." (PMID 22682430, 2012). "In the case that ABCG5/ABCG8 transports vitamin K2, defects in vitamin K2 transport by ABCG5/ABCG8 may be associated with the progression of atherosclerosis in addition to cholesterol transport impairment." (PMID 36839356, 2023). "Besides, another point mutation in the human ABCG5 gene enhancing the ABCG5/8 pathway has been shown to protect against atherosclerosis by increasing cholesterol elimination in the bile and reducing plasma cholesterol levels." (PMID 22682430, 2012). "In our study, the lower ABCG8 and ABCG5 expression in the SUS individuals may be at least partially responsible for the greater susceptibility of this strain to diet-induced atherosclerosis." (PMID 22682430, 2012). "Selection for atherosclerosis susceptibility may have altered the regulation of the ABCG5 gene in the RES strain." (PMID 22682430, 2012). "In atherosclerosis, the downregulation of FXR results in reduced expression of cholesterol transport proteins (ABCG5/ABCG8), ultimately affecting cholesterol efflux and causing cholesterol accumulation." (PMID 39781461, 2025). "These genes are involved in cholesterol metabolism (Abca1, Abcg8, Abcg5, Lpl, Cyp7a1, and Pltp), lipid and atherosclerosis (Abca1, Il1b, Ccl2, and Abcg1), bile secretion (Abcg8, Abcg5, and Cyp7a1), and IL-17 signaling pathway (Ccl7, Il1b, and Ccl2)." (PMID 37301941, 2023). "Activation of the LXRα-ABCA1/ABCG5/8 pathway exerted anti-inflammatory and lipid-regulatory effects during atherosclerosis [reviewed in Fessler (2018)]." (PMID 29593532, 2018). "Furthermore, a study on the mouse has shown that over-expression of ABCG5 and ABCG8 decreases diet-induced atherosclerosis, in association with reduced liver and plasma cholesterol levels." (PMID 22682430, 2012). "In mice with atherosclerosis, AB23A can improve the small intestinal lipid mass spectrum and increase the protein expression of ABCG5/G8 in the proximal jejunum." (PMID 33234731, 2020). "Studies show that the activation of LXRα, one of the LXRs, attenuates the atherosclerosis formation by an increase in expression of cholesterol efflux transporters ABCA1 and ABCG1 in macrophages, and excretion transporters ABCG5 and ABCG8 in enterocytes." (PMID 27399689, 2016).
atherosclerosis (continued). "Thus, overexpression of GATA4 enhances hepatic expression of Abcg5 and Abcg8, and cholesterol excretion to the bile in L-Bmal1−/−Apoe−/− and Bmal1fl/flApoe−/− mice, while reducing MTP expression and atherosclerosis." (PMID 27721414, 2016). "Mice with a defect of the ABCG5/G8 transporter do not develop atherosclerosis." (PMID 36839186, 2023). "Therefore, reduction of TTC39B and enhancement of the LXRα-ABCA1/ABCG5/8 pathway was at least partly responsible for the inhibitory effect of EGCG on the anti-inflammatory and lipid-regulatory effects in high-fat-induced atherosclerosis." (PMID 29593532, 2018). "The mechanism of QSYQ inhibiting atherosclerosis included promoting Treg immigration into atherosclerotic plaque, inhibiting the secretion of IL17 by Th17 in spleen and plaque, blocking oxidized LDL phagocytized by macrophage through CD36, and increasing the expression of LXR-α and ABCG5 in liver." (PMID 29137256, 2017). "Expression of ABCG5 (control diet) and ABCG8 (regardless of dietary treatment) and expression of HMGCR, FDFT1 and SQLE (regardless of dietary treatment) were significantly higher in the atherosclerosis-resistant than in the atherosclerosis-susceptible strain." (PMID 22682430, 2012). "Accordingly, selection for atherosclerosis resistance may not have altered the expression of ABCG5 but rather the expression of some of these receptor genes thus permitting expression of ABCG5 to remain in an up-regulated state in the RES individuals." (PMID 22682430, 2012). "However, liver-specific overexpression of ABCG5/G8 alone did not protect from atherosclerosis development." (PMID 20090943, 2010).
Hypercholesterolemia (23 papers, 2016 to 2026). An increased concentration of cholesterol in the blood. "Heterozygous carriers of pathogenic variants in these genes, but especially ABCG5, have moderate hypercholesterolemia and an increased risk of ASCVD." (PMID 40004987, 2025). "In fact, studies performed widely have reported pathogenic ABCG5/ABCG8 variants to be associated with hypercholesterolemia." (PMID 38122934, 2023). "Hypercholesterolemia in individuals with the ABCG5/G8 mutations have also been shown to respond to ezetimibe treatment effectively." (PMID 36981027, 2023). "A small part has pathogenic variants in ABCG5/ABCG8 in heterozygosity that can cause hypercholesterolemia and should be further investigated." (PMID 38122934, 2023). "Functional studies showed that variant can cause deletion of exon 8 in human ABCG5, and disruptions of ABCG5/ABCG8 genes recapitulated the occurrence of hypercholesterolemia and large platelets in rats." (PMID 34880906, 2021). "Heterozygous ABCG5/8 variants may be underestimated in pediatric patients with hypercholesterolemia." (PMID 36991406, 2023). "Additionally, rare variants in LDLRAP1, LIPA, and ABCG5/8 cause a purely autosomal recessive hypercholesterolemia, in which recessive forms have hypercholesterolemia phenotypically similar to FH." (PMID 30526649, 2018). "In addition, our results suggest that heterozygous ABCG5/8 variants may be underestimated in pediatric patients with hypercholesterolemia, especially for those presented with xanthomas." (PMID 36991406, 2023). "Pediatric patients with hypercholesterolemia could be resulted by heterozygous ABCG5/8 variants." (PMID 36991406, 2023). "In hypophysectomized rats, administration of T3 ameliorates hypercholesterolemia in association with increased hepatic secretion of cholesterol and upregulation of ABCG5 (ATP-binding cassette, subfamily G, member 5) and ABCG8." (PMID 35740254, 2022). "Human mutations in ABCG5 and ABCG8 contribute to the autosomal recessive β-sitosterolemia, a metabolic lipid disorder that causes hypercholesterolemia due to overabsorption of dietary sterols." (PMID 34884779, 2021). "In Spanish patients with hypercholesterolemia, Asn578Ser (rs146534033), Gly288Cys (rs139264483), Arg198Glu (rs141828689), Gly269Arg (rs552803459), and Asn296Ser (rs552803459) in ABCG5 and Gly512Arg (rs376069170) in the ABCG8 gene have been detected." (PMID 31795497, 2019). "Rather, ABCG5/G8 variants can act as a component of an LDL cholesterol genetic risk score and are considered LDL-cholesterol-altering accessary genes that mimic and worsen phenotypes of familial hypercholesterolemia." (PMID 36981027, 2023). "Two heterozygous variants of the ABCG5 gene were found in the proband, and no other variant was observed in the known genes related to hypercholesterolemia." (PMID 34880906, 2021). "We generated an ABCG5/8 double knockout rat, which illustrated that heterozygous ABCG5 variants can lead to large platelets independent of hypercholesterolemia." (PMID 34880906, 2021). "F. Briand fed hypercholesterolemia hamsters with Saccharomyces boulardii CNCM I-745, and CNCM I-745 significantly reduced the expression of ABCG5 and ABCG8 in hypercholesterolemia and increased the expression of HMG CoA-R gene (encoding a rate-limiting enzyme of cholesterol synthesis)." (PMID 33005189, 2020).
Hypercholesterolemia (continued). "Therefore, targeted gene sequencing analysis was performed using custom panels focusing on the exome regions of 21 lipid-associated genes, including ABCG5, ABCG8, and familial hypercholesterolemia-causing genes (LDL receptor, LDLRAP1, PCSK9, and apolipoprotein B)." (PMID 38338819, 2024). "ABCG5/8 transported cholesterol by activating the transcription of LXR, and FXR regulated cholesterol via the SR-B1/CYP7A1/FXR pathway to alleviate hypercholesterolemia in high-fat-diet-fed rats." (PMID 37299563, 2023). "Saccharomyces boulardii CNCM I-745 significantly reduced the expression of ABCG5 and ABCG8 in hypercholesterolemia and increased the expression of HMG CoA-R gene." (PMID 33005189, 2020). "Although ABCG5/G8 variants may increase total and LDL cholesterol levels, they are generally not considered to be the typical defective genes for familial hypercholesterolemia." (PMID 36981027, 2023).
cholestasis (12 papers, 2010 to 2025). Impairment of the bile flow caused by obstruction within the liver, or outside the liver in the bile duct system. "DUOX2 and ABCG5 play prominent roles in cholestasis which is associated with Barnesiella and Parabacteroides." (PMID 36409145, 2022). "Recent studies have reported that Abcg5 deficient mice were more susceptible to cholestasis compared to normal, and that ABCG2 serves as a bile acid and cholesterol transporter." (PMID 25798860, 2015). "Moreover, mutations in Baat, Abcg5 or Abcg8 have been shown to be involved in the development of cholestasis in humans." (PMID 24112857, 2013). "Cholesterol extraction from the canalicular membrane subsequently leads to decreased membrane cholesterol content and cholestasis, also reducing the normal Abcg5/8 mediated cholesterol secretion into bile." (PMID 20126555, 2010). "For example, TNF-α can inhibit the transcription of the tubule bile acid transporter Abcb11, bilirubin outlet Abcc2, and sterol transporter Abcg5/8 in intestinal inflammation, cholestasis, or the activation of hepatic macrophages, and thus affect the expression of transporters." (PMID 35163972, 2022). "IL-1β increases hepatocyte NF-κB signaling, which interferes with farnesoid X receptor and liver X receptor bonding to respective promoters of canalicular bile and sterol transporter genes (Abcc2, Abcb11, and Abcg5/8), resulting in transcriptional suppression and subsequent cholestasis." (PMID 29643332, 2018). "In this study, the expression of ABCG5/8 in the ANIT group was lower than that of the CON group, and cholestasis developed." (PMID 36744213, 2022).
dyslipidemia (9 papers, 2020 to 2025). "To investigate the associations of ABCG5/G8 variants with cardiometabolic traits and the risks of metabolic syndrome and gallstone disease, we first selected candidate variants within the coding and promoter region of ABCG5/G8 among 1478 TWB participants with WGS data." (PMID 36981027, 2023). "Evidence shows that arachidonic acid is associated with dyslipidemia and cholesterol-associated lipoprotein metabolism and that arachidonic acid increased plasma concentrations of TC and ApoB, as well as elevated ApoB protein expression and decreased protein expression of ABCG5/8 in mice." (PMID 39372201, 2024). "Previous genetic association studies have shown associations between ABCG5/G8 polymorphisms and triglyceride, HDL, and VLDL cholesterol levels, insulin sensitivity, and metabolic syndrome." (PMID 36981027, 2023). "In analyses of human and animal models, ABCG5/G8 have also been shown to affect various cardiometabolic traits and disorders, such as lipid and glucose metabolism, blood pressure control, metabolic syndrome, and fatty liver disease." (PMID 36981027, 2023). "Considering that pregnant women with ICP are also prone to other metabolic features, especially dyslipidemia, ABCG5 mRNA expression was determined." (PMID 34638773, 2021). "As for the genes involved in lipid metabolism, Pla2g2d, Lipo3, and Naaa were significantly upregulated, promoting anabolism, while lipid-transport-related genes, such as Abcg5, Apo3, and Stard5, were down-regulated, leading to lipid surplus and diverse metabolic syndromes, such as obesity." (PMID 39007149, 2024). "The phenotype of FH is also affected by other genes, including ATP-binding cassette subfamily G member 5 (ABCG5), ATP-binding cassette subfamily G member 8 (ABCG8), and apolipoprotein E (APOE), which are known to be causal genes of recessive types of inherited dyslipidemia." (PMID 38540356, 2024). "We tested whether ABCG5/G8 variants in TWB participants were also associated with various cardiometabolic traits and metabolic syndrome." (PMID 36981027, 2023). "In addition, variants in genes causing other dyslipidemias showing phenotypes overlapping with FH may mimic FH in patients without causative variants (FH-phenocopies; ABCG5, ABCG8, CYP27A1 and LIPA genes) or act as phenotype modifiers in patients with a pathogenic variant in a causative gene." (PMID 36834635, 2023).
Insulin resistance (9 papers, 2018 to 2025). Increased resistance towards insulin, that is, diminished effectiveness of insulin in reducing blood glucose levels. "Specifically, hepatic insulin resistance leads to the activation of the forkhead transcription factor (FoxO1), which promotes the overexpression of bile cholesterol transport proteins Abcg5 and Abcg8, resulting in excessive cholesterol secretion into bile." (PMID 39944962, 2025). "In the liver, insulin resistance promotes cholesterol secretion through ABCG5/8 induced aberrant expression of FOXO1." (PMID 40748974, 2025). "In hepatocytes, insulin resistance induces abnormal expression of the transcription factor forkhead box protein O1 (FOXO1) through the ABCG5 and ABCG8 genes to promote cholesterol secretion." (PMID 37396166, 2023). "Our findings support previous studies that have identified the upregulation of Abcg5 and Abcg8 in response to insulin resistance and an HF diet." (PMID 30526554, 2018). "On one hand, insulin resistance may increase biliary cholesterol secretion by upregulating hepatic cholesterol transporters ABCG5/8." (PMID 41287115, 2025). "In patients with diabetes, hepatic insulin resistance (IR) could promote CG formation by upregulating the expression of hepatic ABCG5 and ABCG8." (PMID 38268006, 2024).
cholelithiasis (8 papers, 2021 to 2025). The presence of crystallized deposits forming in the gallbladder or biliary tree, primarily composed of cholesterol, bilirubin, and bile. "Common mutations in ABCG5 confer the majority of the genetic risk for cholelithiasis, accounting for approximately 25% of the total risk." (PMID 40428345, 2025). "ASGR1 inhibitors may increase the risk of cholelithiasis through elevating biliary cholesterol excretion, similar to adenosine triphosphate-binding cassette transporters G5/8 (ABCG5/8)." (PMID 37400795, 2023). "ABCG5/8 has been found to contribute ~75% biliary cholesterol secretion, and its genetic mutation, or dysregulation would strongly disturbs cholesterol secretion and cholelithiasis progression." (PMID 34803510, 2021). "Genes such as ABCG5/G8, ABCB4, ABCB11, and UGT1A1 are crucial in increasing the lithogenicity of bile and are strongly associated with various forms of cholelithiasis, especially cholesterol-based." (PMID 40149408, 2025). "Genetic colocalization study identify one SNP locating at the ABCG5/ABCG8 locus is shared by both campesterol and cholelithiasis, indicating the potential therapeutic target in preventing cholesterol gallstone formation." (PMID 38347599, 2024). "Furthermore, even after excluding ABCG5/8 variants from the LDL-PGS, the association with the risk of cholelithiasis was not attenuated." (PMID 36575460, 2022).
hyperlipidemia (7 papers, 2020 to 2025). "Second, alternative causes of hyperlipidemia should be considered—four unique P and LP variants in other genes (CYP27A1, ABCG5, ABCG8, and LIPA) were found in seven patients (2% of all patients with positive monogenic variant), which increases the overall diagnostic yield to 23.6%." (PMID 39769230, 2024). "Our correlation analysis showed increased fecal β-sitosterol and cholesterol sulfate levels in the intervention group, suggesting that HM018 upregulates ileal Abcg5/8 transcription to enhance sterol excretion via TICE, thereby alleviating hyperlipidemia." (PMID 40535017, 2025).
Obesity (7 papers, 2012 to 2024). Accumulation of substantial excess body fat. "These genes include CD36 (HDL-C), RPTOR (obesity) and ABCG5/ABCG8 (low-density lipoprotein cholesterol (LDL-C) and total cholesterol)." (PMID 26021296, 2015). "Our data on the downregulation of Abcg5/8 confirm similar findings in a diet-induced obesity mouse model with a high fat but cholesterol-free diet." (PMID 22394543, 2012). "Notably, the absence of ABCG5/ABCG8 (ATP binding cassetteG5/G8) reduces biliary cholesterol secretion and results in hepatic cholesterol accumulation, acceleration of obesity, and exacerbation of NAFLD in mice." (PMID 29769539, 2018).
diabetes (6 papers, 2013 to 2025). "Furthermore, in response to increased cholesterol synthesis that occurs with diabetes, feed-forward activation of ABCG5/8 enzyme activity stimulates the conversion of cholesterol to bile acid." (PMID 27929393, 2016).
xanthoma (6 papers, 2023 to 2026). A non-neoplastic disorder characterized by a localized collection of histiocytes containing lipid. "Patients were categorized based on the presence of xanthomas and the type of variants in the ABCG5 or ABCG8 genes." (PMID 39860331, 2025). "Among the 15 individuals who were diagnosed with type 2 sitosterolemia and who carried ABCG5 variants, a large majority (11, 73.3%) had developed xanthomas, and a significant number (5, 33.3%) were affected by arthritis." (PMID 38509578, 2024). "50.00% (3/6) of the patients with xanthomas were confirmed having at least one ABCG5/8 variant, indicating that xanthomas are probably an indicator of ABCG5/8 variant." (PMID 36991406, 2023).